TNF (tumor necrosis factor)
Diseases named in the same sentence as TNF in open-access papers (continued):
Sharing a sentence is not in itself a finding about the gene and the disease.
tumor (continued). "The tumor inhibition rate of tumor and repair rate of IFN-γ, TNF-α, and TGF-β1 all increased, indicating a positive therapeutic effect of PG–OJ on A549 tumor-bearing mice." (PMID 38257247, 2024). "For example, in cervical cancer, TNF-α and TGF-β are shown to be working cooperatively to induce EMT and tumor stemness through NF-κB/Twist axis." (PMID 38935134, 2024). "The TNF+/VEGFA+ ratio was high in adjacent normal tissues (ratio=4), which was lower than that in tumor tissues, with the lowest ratio occurring at the tumor rim (ratio=1.2)." (PMID 39840068, 2024). "For example, cytokines secreted by TANs such as IL-17, IL-23, and TNF-α activate the protein kinase B/p38(Akt/p38) pathway, which enables mesenchymal stem cells (MSC) to transform into TAFs and ultimately promote tumor cell proliferation and metastasis." (PMID 38279145, 2024). "LILRB4 blockade restored IL-2 production in HDVax-induced cells and enhanced their expression of IFNγ/TNF and CD40L in both T3 and F244 tumour models." (PMID 39048822, 2024). "First, pro-inflammatory cytokines such as TNF-α, IL1, and IL6 promote tumor cell death and inhibit tumor growth." (PMID 38534922, 2024). "Tumor macrophages are also direct producers of VEGF, along with other angiogenic factors like tumor necrotic factor α (TNFα), basic fibroblast growth factor (bFGF), IL-8, and IL-1." (PMID 38455762, 2024). "Differential gene expression results revealed five genes (IDO1, IL6, TNF, CD209, and FOXP3) that were, on average, upregulated ≥ 2-fold or downregulated ≤ –2-fold in treated tumor regions relative to untreated tumor regions." (PMID 39335552, 2024). "On the other hand, the genes TNF and KRT76 were significantly upregulated and overexpressed in the T1 group, which indicates their role as tumor suppressor genes, inhibiting tumor progression and invasion." (PMID 38539520, 2024). "CAR-T cells were shown to effectively kill tumor cells, and high levels of cytokine secretion such as IFN-γ, IL-2 and TNF-α were found." (PMID 38339374, 2024). "These tumor-infiltrating CD8+ T cells were functional CTLs, as evidenced by the expression of granzyme B (GZB) and the effector cytokines IFN-γ and TNF-α." (PMID 38349740, 2024). "CD4+ T cells can present tumor antigen epitopes; promote the activation of CD8+ T cells and the effector and memory functions of CTLs; and secrete IFN-γ, IL-2, and TNF-α to improve CTL activity and assist in killing tumor cells." (PMID 39408814, 2024). "Combined OGT inhibitor with anti-PD-L1 antibody markedly suppressed tumor growth and increased CD8+ T cells and production of IFN-γ and TNF-α in tumor." (PMID 38168435, 2024). "BCG enters tumour cells through phagocytosis to stimulate the production of cellular immune factors such as MCP‐1, MDC, TNF and IL‐10, resulting in the weakening of tumour cell differentiation or stopping the replication cycle." (PMID 38165009, 2024). "We further found that LSD1 shRNA anti-CD19 CAR-T cells had comparable levels of TNF-α secretion to RNAU6 anti-CD19 CAR-T cells, but secreted more IFN-γ, which is capable of indirectly killing tumor cells and affecting immune regulation." (PMID 39872520, 2024). "Within the TME, activated CD8+ T cells are critical for tumor cell eradication, releasing perforin, Fas, and cytokines such as TNF-α and IFN-γ, which exert anti-tumor effects." (PMID 39648231, 2024). "Through ELISA analysis, elevated expression of proinflammatory cytokines (such as TNFα, IL-8, GRO, MCP-1, and IL-1a) was observed in tumor samples compared to normal mucosa." (PMID 38835386, 2024). "Upon recognizing tumor antigens, CAR T cells secrete pro-inflammatory cytokines, such as IL-2, IFN-γ, and TNF-α, to regulate cell growth, activation, and differentiation." (PMID 38683232, 2024). "Co-culture of Bregs with tumour-infiltrating follicular cytotoxic CD8+ T (Tfc) cells increased Tfc expression of IL-10 and reduced Tfc expression of pro-inflammatory IFN‐γ, TNF, and IL-2 in NSCLC patients." (PMID 39346706, 2024).
tumor (continued). "The HER2-CD3-Fc bsAb in the culture significantly enhanced T cell secretion of IFN-λ, TNF-α, and granzyme B in response to NCI-H460 tumor cells in a dose-dependent manner." (PMID 39066446, 2024). "Further analysis of the spleen and TDLNs of these vaccinated mice validated a significant ex vivo activation of tumor‐pulsed splenocytes, determined by an increased proportion of IFN‐γ+ and TNF‐α+ CD44+ CD8+ T cells." (PMID 38666427, 2024). "Researchers also confirmed its tumor-promoting function in epithelial ovarian cancer (EOC), where it activates the Hedgehog pathway with increased inflammatory factors such as TNF-α and IL-1β." (PMID 39497925, 2024). "The bsAb induced potent T-cell-directed cytotoxicity, along with secretion of IFN-λ, TNF-α, and granzyme B, against various types of HER2-positive tumor cells in vitro, including A549, NCI-H460, SKOV-3, A1847, SKBR3, and MDA-MB-231." (PMID 39066446, 2024). "Human mDCs have the ability to kill tumor cells via TRAIL, FasL expression, or TNF-α, perforin, and granzyme secretion." (PMID 38903193, 2024). "There is evidence that prolonged TNF-α exposure can increase the proportion of OSCC cells with cancer stem cell phenotypes, which increases their tumor sphere-forming ability." (PMID 38644421, 2024). "Activated CD8+ T cells and NK cells in turn can secrete cytokines TNF-α, GM-CSF and IFN-γ, and chemokines CCL4, CCL5 and CCL23 to recruit even more immune cells to the TME to help suppress tumor growth." (PMID 38935134, 2024). "The tumor-immune cells microenvironment augments PD-L1 expression with pro-inflammatory cytokines, such as IFN-γ, tumor necrosis factor α (TNF-α), IL-10, interleukin-1 (IL-1) and interleukin-6 (IL-6)." (PMID 38384472, 2024). "The expression of IL‐2, TNF‐α, IFN‐γ increased in BPCP plus laser group, proving that BPTT activates the immune response and alleviates the immunosuppressive tumor microenvironment." (PMID 37984863, 2024). "The secretion of the serum killer cytokines, TNF-α and IFN-γ, in tumour-bearing nude mice in the experimental group was higher than that in the empty vector and control groups (P < 0.05)." (PMID 39107717, 2024). "CD8+ TIL polyfunctionality was predicated on coordinate CD8+ TIL responder intracellular expression of IFNγ, TNFα, and IL2 as determined by flow cytometry after a 5 h in vitro stimulation with either tumor cells or PVECs." (PMID 39066414, 2024). "Th1 cells primarily secrete cytokines such as TNF-α, IFN-γ and IL-2, playing a crucial role in anti-tumor immunity." (PMID 38792234, 2024). "And M1 macrophages are associated with enhanced antigen presentation, increased secretion of pro-inflammatory cytokines (e.g., TNF-α, IL-12), and improved recruitment and activation of CD8+ T cells, collectively promoting anti-tumor immunity." (PMID 39868376, 2024). "This enhances the cytotoxic activity of tumor-infiltrating CD8+ T cells and promotes the secretion of GzmB, IFN-γ, and TNF-α." (PMID 39811730, 2024). "TNFα is also a classic NF-ĸB pathway activating cytokine, and after upregulation of TNFα by SCGN it can further activate the NF-ĸB pathway by acting on tumor cells." (PMID 39664565, 2024). "CXCL9, CXCL10, and CXCL11 are mainly secreted by myeloid lineages and tumor cells in the TME responding to IFN-γ, and this process is synergistically enhanced by TNF-α." (PMID 39076974, 2024). "With intracytoplasmic DNA, cGAS-STING agonist can increase the production of interleukin 6 (IL-6), tumor necrosis factor (TNF) and interferon (IFN) and play a regulatory role in inflammation and tumor treatment." (PMID 39125107, 2024). "Tumor necrosis factor alpha (TNF-α), EGF, and other cytokines promote abnormal proliferation of tumor cells by activating signaling pathways regulating cell proliferation, including MAPK and PI3K/AKT transduction." (PMID 38828408, 2024).
tumor (continued). "TNF-α producing Th cells and tumoricidal CD8+ T cells migrate into the tumor site, contact tumor cells, and release perforin that mediates killing cancer cells." (PMID 38920557, 2024). "There are studies assessing the possibility of activating neutrophils using a cocktail consisting of tumor necrosis factor, CD40 agonist, and tumor-binding antibody." (PMID 39769334, 2024). "These BiKEs successfully stimulated EGFR-positive tumor cell killing and IFN-γ and TNF-α secretion by NK cells." (PMID 39339180, 2024). "In line with the manifestation of symptoms, the amounts of IL-2, TNF-α, and IFN-γ in the tumor-free stCAR T-cell group were higher than in the tumor-engrafted mice and came close to those observed in the presence of monocytes." (PMID 38514793, 2024). "These fusion proteins aim to target tumor cells and the TME with greater specificity than their proinflammatory cytokine payloads alone, which include IL‐2, tumor necrosis factor (TNF), and IL‐12." (PMID 39618102, 2024). "Together, these findings suggest that regulatory T cells infiltrate glioblastoma tumors, promoting the TGF beta, TNF via NF-kB, and IL6/JAK/STAT3 signaling pathways and thereby increasing mesenchymal transition of tumor cells." (PMID 38981682, 2024). "Lower expression of HOIP can lead to increased production of caspase-3 and caspase-8 in tumor cells mediated by TNF and IFN-γ, inducing tumor cell apoptosis." (PMID 39223632, 2024). "In mice, the targeted delivery of IL2, TNF, and IL12 led to a potentiation of the cytokine payload as a result of increased density and activity of tumor resident T cells and NK cells, capable of neoplastic cell recognition." (PMID 38448543, 2024). "Studies have confirmed that chitosan-based biomaterials can promote mitochondria-induced apoptosis, promote tumor cell antioxidants, and reduce the production of IL-8, IL-6, TGF-β, and TNF-α to achieve anti-inflammatory effects." (PMID 39161903, 2024). "This phenomenon has also been observed in PVRIG knockout mice, in which tumor-infiltrated T cells exhibit enhanced IFN-γ and TNF-α production." (PMID 38554184, 2024). "Some studies suggest that in certain situations, mast cells can release immune cytokines and mediators like tumor necrosis factor (TNF) and interferons to activate immune cells and promote anti-tumor immune responses." (PMID 38734657, 2024). "This resulted in a 63.4% transfection rate of macrophages and 27.2% of DCs located in the tumor tissue, which mediated tumor control, and TNF-α and IFN-γ were detected in the tumor lysate." (PMID 39061247, 2024). "Flow cytometry revealed specific depletion of the hepatic F4/80 high CD11bint macrophage population, and its exhaustion led to a remarkable increase in tumor-infiltrating MAIT cells and increased expression of IFN-γ, TNF-α, and granzyme B." (PMID 39068459, 2024). "Two prospective phase II trials showed that the DC-CIK can induce the proliferation of autologous tumor-specific T cells and the expression of IFN-γ, IL-2, and TNF-α in CD4+ T cells." (PMID 38476223, 2024). "Our results revealed that DASH CAR-T, which secreted higher levels of IFN-γ and TNF immediately after antigen presentation compared to conventional CAR-T, exhibited greater tumor-eradication ability in vitro and in vivo." (PMID 39772010, 2024). "Infections with S. typhimurium and Clostridium significantly increase neutrophils, which secrete more TNF-α and TRAIL, enhancing the immune response and tumor cell death." (PMID 39594765, 2024). "In this study, we were able to identify the sites of the molecules of the proinflammatory cytokine TNF and its TNFR1, which are necessary for the two-stage cytotoxic signal transduction required for tumor cell killing." (PMID 38612709, 2024). "Abundant CCL22-expression by tumor cells has been reported following combined crosstalk with NK cells and macrophages via the proinflammatory cytokines IFN-γ, TNF-α and IL1β." (PMID 39232378, 2024).
tumor (continued). "Studies have reported that TAMs increase glycolysis in NSCLC cells through TNF-α secretion and promote hypoxia through AMP-activated protein kinase and PGC-1α activation, which in turn sustains tumor development." (PMID 39065562, 2024). "We induced dMMR tumor cell lines DLD1 or HCT116 to PANoptosis with IFN-γ, TNF-α, or co-treatment of IFN-γ and TNF-α compared with pMMR tumor cell lines SW480 or HT29." (PMID 38740747, 2024). "In summary, NK cells, classified as innate immune cells with cytotoxicity against tumor and virus-infected cells, also secrete signaling substances like IFN-γ, TNF-α, and chemokines." (PMID 38474724, 2024). "Conversely, the combined administration of both antibodies significantly inhibited tumor growth, amplified the presence of tumor-infiltrating CD8+ T cells, and augmented the production of IFN-γ and TNF-α by these T cells." (PMID 39015563, 2024). "Vδ1+ and Vδ2+ γδ T cells recruited to the TME further exert tumor killing effects through perforin/granzyme-, IFN-γ/TNF-α-, death receptor ligand-, and ADCC pathway-mediated cytotoxicity." (PMID 38515134, 2024). "Exosomes released by tumor cells can activate the TLR/MyD88/NF-κB signaling pathway in macrophages, prompting the release of pro-inflammatory cytokines (such as IL-6, TNF-α, GCSF, and CCL2)." (PMID 38347830, 2024). "Th1 cells secrete cytokines like interferon-gamma (IFN-γ) and tumor necrosis factor-alpha (TNF-α), promoting cytotoxic T cell proliferation and tumor cell eradication." (PMID 39906672, 2024). "Anti-TNF-α and anti-IL-1β in SPP1-OE supernatant had similar effect on tumor cells compared with VGX-1027." (PMID 39726047, 2024). "Adipokines and inflammatory cytokines produced by adipocytes and macrophages, such as adiponectin, leptin, TNFα, and IL6, can promote tumour growth by cell proliferation, migration, and neo-angiogenesis." (PMID 38339282, 2024). "In a study of CAR-T cell therapy combined with infusing aAPC, aAPC infusion promoted the specific recognition of CAR-T cells to tumor cells and released more IFN-γ, TNF-α, and IL-2." (PMID 39372416, 2024). "Circulating lymphocytes have an anti-tumor effect and promote the death of cytotoxic cells by producing cytokines, such as INF-γ and TNF-α." (PMID 39010005, 2024). "NK cells recognize autologous or allogeneic cells through the MHC-I complex, enabling them to eliminate tumor cells through various pathways, including the classical perforin–granzyme pathway, Fas–FasL pathway, ADCC pathway, and TNF-α–IFN-γ pathway." (PMID 39456702, 2024). "In the presence of tumour cells, the MSLN CAR‐NK cells show increased secretion of IFN‐γ and TNF‐α, as well as elevated CD107a expression level compared with induced NK cells." (PMID 39136096, 2024). "Mechanistically, Y-A targets the TNF-α/STAT3 pathway, inhibiting STAT3 and JAK2 phosphorylation, thereby activating apoptotic pathways and suppressing tumor cell growth." (PMID 39056720, 2024). "Briefly, SPP1 + Mac-derived TNF-α and IL-1β promote the expression of OPN in both macrophages and tumor cells." (PMID 39726047, 2024). "Thus, another goal of this study was to determine whether HIFU treatment causes an influx of immune cells into the tumor area and the expression of pro-inflammatory cytokines: interleukin-1α (IL-1α), interleukin-1β (IL-1β), interferon γ (IFN-γ), and tumor necrosis factor α (TNF-α)." (PMID 39199617, 2024). "Compared with conventional anti-MSLN CAR-T cells, CAR-T cells coexpressing CCR2b exhibited increased CCL2-induced calcium flux and transport, increased levels of IL-2, IFN-γ, and TNF-α, and enhanced cytotoxicity against MSLN+ tumor cells in vitro." (PMID 39023820, 2024). "Damages to the glycolysis pathway in tumor cells leads to the increase in ROS level, which downregulates c-FLIP, the key inhibitor of tumor necrosis factor-α-induced cell death and enhances CTLs-mediated bystander killing." (PMID 38270700, 2024).
tumor (continued). "Thalidomide and lenalidomide combine immunomodulatory and anti-angiogenic effects by inhibiting NF-κB activity, TNF-α expression, and (to a lesser extent) FGF-2 and VEGF expression in various tumor cell types." (PMID 39796700, 2024). "Traditionally, macrophages that express high levels of tumor necrosis factor (TNF), inducible nitric oxide synthase (iNOS), or MHC Class II molecules are considered to have anti-tumor effects." (PMID 39075441, 2024). "The PMN-MDSCs-derived TNF rewire CXCL1 overproduction by cancer cells that in turns led to dysfunction and spatial exclusion of T cells from tumor core." (PMID 38817612, 2024). "Previous studies have demonstrated the requirement of IFNγ and IL1/TNF cytokines for tumor NOS2/COX2 expression, in which correlations between tumor NOS2 and CD8 expressions were observed at the tumor stroma interface." (PMID 39356141, 2024). "Similar results were observed for Tumor Necrosis Factor alpha (TNF-α) and Interleukine-6 (IL-6) within tumor, 2 cytokine genes coding for pro-inflammatory." (PMID 38426110, 2024). "Our previous studies demonstrated that TNFAIP2 is a KLF5 downstream target gene in response to TNFα and TNFAIP2 knockdown inhibited HCC1806 xenograft tumor growth." (PMID 39532855, 2024). "The effect was correlated with an increase in IFNγ and TNFα production from splenocytes, a decrease in proliferation Ki-67 and micro vascularization CD31 levels, and an increase in tumor necrosis." (PMID 38803496, 2024). "MMP-9, furthermore, has the ability to activate key growth factors, including transforming growth factor β (TGF-β), VEGF, and tumor necrosis factor α (TNF-α), thereby promoting tumor growth and angiogenesis." (PMID 39769318, 2024). "Studies on the role of TLRs in NSCLCs show that activation of TLR-4 in NSCLC cells leads to increased regulation of pro-inflammatory cytokines and chemokines (TNF-α or CCL2), which contribute to the immunosuppressive nature of the tumor microenvironment." (PMID 39124797, 2024). "Th1 cells assist CD8+T cells and secrete cytokines such as tumor necrosis factor-alpha (TNF-α), IFN-γ, and IL-2 to enhance the ability of CD8+T cells to target and kill tumor cells." (PMID 38550587, 2024). "At the study evaluation timepoint of 2 h post H-FIRE, we observed differential gene expression changes in the genes IDO1, IL6, TNF, CD209, and FOXP3 in treated tumor regions relative to paired untreated tumor regions." (PMID 39335552, 2024). "Inflammatory cytokines such as IFN-γ, tumor necrosis factor-alpha (TNF-α), and various interleukins (IL-6, IL-10, and IL-27) also play significant roles in PD-L1 expression within the tumor microenvironment (TME)." (PMID 38474186, 2024). "Malaria infection increases the level of TNF-α and interferon-gamma (INF-γ), the activation of natural killer cells, the proliferation of tumor-specific T cells, and the activity of CD8+ T cells in mice with Lewis lung cancer." (PMID 38774541, 2024). "Tumor necrosis factor-α (TNF-α) is a multifunctional cytokine known as a critical regulator of inflammation and tumor progression." (PMID 38612922, 2024). "Subsequently, we performed IHC staining for T cells and markers related to tumor immune or angiogenesis function, including CD3, CD8, CD31, IFN-γ, TNF-α, and PD-L1." (PMID 38748269, 2024). "After expansion, potential effector functions of γδ T cells were demonstrated by IFN-γ, TNF-α and granzyme B production upon PMA/ionomycin stimulation and effective killing capacity of multiple tumor cell lines was confirmed in killing assays." (PMID 38426099, 2024). "Type I NKT cells play a role in anti-tumor immunity by producing Th1 cytokines such as IFN-γ and TNF, which recruit NK cells and CD8+ T cells, mediating anti-tumor functions." (PMID 38755133, 2024). "Their functions are driven by pro-inflammatory (e.g., iNOS, TNFα, IFN) and anti-inflammatory (e.g., IL-4, IL-10, IL-13, CD206, ARG1) cytokines, impairing or favoring tumor growth." (PMID 39278921, 2024).